PCSK9 (proprotein convertase subtilisin/kexin type 9)
Diseases named in the same sentence as PCSK9 in open-access papers (continued):
Sharing a sentence is not in itself a finding about the gene and the disease.
hyperlipidemia (continued). "Herein, a novel copolymer for delivery of Cas9‐mRNA/ single‐guide RNA (Cas9‐mRNA/sgRNA) in vitro and vivo, using carboxylesterase‐responsive cationic triadic copolymeric nanoparticles targeted proprotein convertase subtilisin/kexin type 9 (PCSK9) for hyperlipidemia amelioration is reported." (PMID 37083231, 2023). "In oncology, Canakinumab increases clearance of drugs metabolized by drug transporter CYP3A422; In cardiology, statins increase clearance of Evolocumab, an anti-proprotein convertase subtilisin/kexin type 9 (PCSK9) mAb in adults with hyperlipidemia, likely via inducing additional PCSK9 expression." (PMID 38016958, 2023). "Moreover, inhibitors of PCSK9, designed to regulate hyperlipidemia by impacting LDL absorption and elimination in liver cells, have been effective in managing the hyperlipidemia linked with nephrotic syndrome." (PMID 38136203, 2023). "Besides statins and other lipid-modifying drugs, PCSK9 monoclonal antibodies are known to reduce hyperlipidemia." (PMID 35806908, 2022). "To assess whether the MHC-IIhiCD11c+CD206- macrophages are monocyte-derived, we induced hyperlipidemia by PCSK9-AAV infection and WD feeding to Ccr2+/+ or Ccr2−/− mice." (PMID 36115863, 2022). "In continuation of the goals of this paper, it is advised that further attention be given to these endpoints and parameters to help researchers and clinicians solidify the comprehensive role of PCSK9 inhibitors in populations with statin intolerance or statin-resistant hyperlipidemia." (PMID 36554779, 2022). "In contrast, PCSK9 inhibitors may be the preferred LDL-C-lowering drug among males with hyperlipidemia to prevent prostate cancer." (PMID 35151363, 2022). "Further research is needed to verify the clinical value of injecting PCSK9 inhibitors into patients with severe hyperlipidemia to assess whether they improve their prognosis." (PMID 36140421, 2022). "In addition, proprotein convertase subtilisin/kexin type 9 (Pcsk9) and cholesterol 7α-hydroxylase (Cyp7a1) were the key genes both enriched in the cholesterol metabolism pathways in hyperlipidemia rats treated with HTJZD." (PMID 33936248, 2021). "Free plasma PCSK9 levels from 9 hyperlipidemia subjects were measured with ELISA." (PMID 33632254, 2021). "More recently, for the secondary prevention of hyperlipidemia, the Niemann–Pick transport inhibitor ezetimibe, and inhibitors of the proprotein convertase subtilisin/kexin type 9 (PCSK9) have become available and allow for even further reductions in LDL cholesterol in high-risk patients." (PMID 33917591, 2021). "Moreover, a previous clinical study reported that proprotein convertase subtilisin/Kexin type 9 (PCSK9) inhibitors, primary indicated for the treatment of hyperlipidemia, also reduce the risk of AAA." (PMID 34436496, 2021). "Among six candidate targets (Srebp-1c, Cyp7a1, Cyp3a9, Pcsk9, Insr, and Gck), Srebp-1c and Insr may play central role in the treatment of hyperlipidemia." (PMID 33936248, 2021). "Hyperlipidemia is a known risk factor for CAD and can be treated with statins and PCSK9 inhibitors." (PMID 33209524, 2020). "The effect of plasma PCSK9 levels on hyperlipidemia in PNS patients." (PMID 32349585, 2020).
hyperlipidemia (continued). "Hyperlipidemia regulates neuronal apoptosis in the hippocampal CA3 of mice by increasing PCSK9 and BACE1 expression, which may elucidate the role of lipid metabolism disorder in AD pathogenesis." (PMID 33192735, 2020). "The Preferred Reporting Items for Systematic Reviews and Meta-Analyses (PRISMA) checklist was utilized throughout the compilation of this systematic review to answer the research question: Is there a disparity between race and gender in hyperlipidemia treatment with statin versus PCSK9 inhibitors?" (PMID 33209524, 2020). "In summary, PCSK9 expression levels in newly diagnosed PNS patients were significantly higher than those in healthy controls, and linearly positively correlated with TC and LDL-C abundance, suggesting that PCSK9 is involved in the development of hyperlipidemia in PNS." (PMID 32349585, 2020). "The aim of the current review is to summarize the current knowledge on the importance of free fatty acid metabolism on myocardial ischaemia/reperfusion injury and to provide an update on recent evidence on the role of hyperlipidemia and PCSK9 in myocardial infarction and cardioprotection." (PMID 33262707, 2020). "However, Pcsk9 is increased in the dentate gyrus after transient cerebral ischemia and in a mouse model of hyperlipidemia where neuronal apoptosis occurs in the hippocampus." (PMID 32244519, 2020). "PCSK9 inhibitors seem to be the strongest ally in the war against hyperlipidemia." (PMID 29209441, 2017). "The issue of healthcare systems either facilitating or hindering optimal delivery of hyperlipidemia management will now be amplified by the paradigm-shifting improvement in LDLC lowering by the PCSK9 class of medications at an annual price of $14,000–14,600 per patient." (PMID 26968977, 2016). "Proprotein convertase subtilisin/kexin type 9 (encoded by PCSK9) plays a well-known role in the regulation of low-density lipoprotein (LDL) receptors, and an inhibitor of this enzyme is a promising new therapeutic for hyperlipidemia." (PMID 25904937, 2015). "In addition to proinflammatory cytokines, high-fat diet (HFD)-induced hyperlipidemia also enhances PCSK9 expression potentially by modulating Toll-like receptor (TLR) 4 and its downstream signaling factors myeloid differentiation primary response gene 88 (MyD88) and nuclear factor kappa-B (NF-κB)." (PMID 39963241, 2025). "AF identification in individuals with prior hyperlipidaemia prompted a change in management for 17: (re-)introduction of lipid-lowering therapy, initially statin (n=13), supplemented with ezetimibe (n=1), or statin replaced by a PCSK9 inhibitor together with ezetimibe (n=1), or increased dose (n=2)." (PMID 38131308, 2024). "Similarly, PCSK9 and APOB were associated with hyperlipidemia in the UK Biobank." (PMID 39474612, 2024). "Additionally, previous studies have shown that AAV8-PCSK9 injection results in lower Pcsk9 mRNA expression in the liver and lower PCSK9 levels in the serum of female mice than male mice, and therefore male mice showed greater hyperlipidemia." (PMID 37937642, 2023). "Consequently, co-delivery of PCSK9 and mTOR inhibitors may provide a promising strategy for avoiding tumor chemotherapy-induced hyperlipidemia, but such a combination is rarely reported." (PMID 37896137, 2023). "Therefore, we speculate that for PNS patients, when levels are increased to 255.05 ng/ml, PCSK9 participates in the development of hyperlipidemia." (PMID 32349585, 2020). "Thus, an anti-PCSK9 antibody is well known as an anti-hyperlipidemia drug." (PMID 29438441, 2018).
hyperlipidemia (continued). "Given the established positive correlation between elevated serum PCSK9 levels, SURF4 upregulation, and hyperlipidemia—particularly through SURF4-mediated hepatic lipoprotein packaging and subsequent metabolic inactivation—we measured serum PCSK9 levels." (PMID 41041130, 2025). "Monoclonal antibodies Evolocumab and Alirocumab, approved for hyperlipidemia by the EMA and FDA, demonstrate PCSK9’s potential as a therapeutic target in cancer." (PMID 40328788, 2025). "Compared with the T2D group, the T2D with hyperlipidemia group had significantly higher levels of TG, TC, LDL-C, ApoB/ ApoA1, FBG, HbA1c, hs-CRP, and PCSK9." (PMID 39951410, 2025). "Tail vein injection of PCSK9-D377Y AAV8 and western diet feeding induced hyperlipidaemia in C57 mice mimiced the hyperlipidaemic features of ApoE-/-." (PMID 38913045, 2024). "The combination of PCSK9 inhibitors with robust statins like rosuvastatin and atorvastatin markedly decreases LDL-C levels in patients with hyperlipidemia when compared to placebo or monotherapy." (PMID 39975967, 2024). "Although PCSK9 inhibitor therapy is effective for reducing LDL-C levels, the use of PCSK9 inhibitors in patients with hyperlipidaemia is limited." (PMID 39340274, 2024). "Injecting WT C57BL/6 mice with a low dose of AAV8-PCSK9 increased both serum PCSK9 and cholesterol levels only in male mice, whereas 3 times the original dose of AAV8-PCSK9 was required to induce hyperlipidemia in the female mice." (PMID 37937642, 2023). "Proprotein convertase subtilisin/kexin type 9 (PCSK9), which is largely hepatically expressed, blocks low-density lipoprotein (LDL) receptor recycling, also leading to hyperlipidemia." (PMID 36557234, 2022). "While contact allergy showed impairment in the PCSK9 and VLDL-R SNPs, hay fever displayed alterations in the LDL-R and VLDL-R receptor considering both the BMI and the presence of hyperlipidaemia as confounding factors." (PMID 35684151, 2022). "It is best known that PCSK9 binds to LDL-R, leading to their intracellular degradation and then promoting plasma LDL-C levels and hyperlipidemia." (PMID 35498417, 2022). "Although data from various clinical trials firmly show an appreciable mitigating effect of the PCSK9 inhibitor evolocumab on hyperlipidemia in T2DM patients, there are still some concerns regarding the correlation between PCSK9 inhibitors and DM complications." (PMID 34504898, 2021).
hyperlipidemia (continued). "Evolocumab, a novel human monoclonal antibody, inhibits proprotein convertase subtilisin/kexin type 9, a protein that targets low-density lipoprotein-cholesterol (LDL-C) receptors for the treatment of hyperlipidemia." (PMID 29736889, 2018). "Third, although we have detected the interactions of the DOCK7, PCSK9 and GALNT2 SNPs on hyperlipidaemia in this study, many unmeasured environmental and genetic factors still need to be considered." (PMID 26493351, 2016). "In conclusion, the results of the present study suggest that PCSK9 downregulation to ameliorates hyperlipidemia-induced liver inflammation without inducing sever lipid accumulation." (PMID 39963241, 2025). "Inhibition of PCSK9 is used for hyperlipidemia patients where statin therapy is not suitable due to muscle lysis (~20% humans)." (PMID 40563926, 2025). "The LDL levels were similar between patients with and without a diagnosis of hyperlipidemia because all the patients with that diagnosis were treated with one of more therapies including statins, ezetimibe, PCSK9 inhibitors and lifestyle changes." (PMID 39814831, 2025). "The PCSK9 inhibitor evolocumab has been shown to significantly reduce LDL-C and other lipid markers, providing substantial therapeutic benefits for T2D patients with hyperlipidemia." (PMID 39951410, 2025). "Inclisiran, a small interfering RNA targeting hepatic PCSK9 (proprotein convertase subtilisin/kexin type 9), is effective and well tolerated in adult patients with hyperlipidemia; however, it has not yet been studied in pediatric patients." (PMID 40391436, 2025). "A recent investigation suggests PAI-1 is directly involved in the development of diet-induced hyperlipidemia and hepatic steatosis through regulation of PCSK9 (proprotein convertase subtilisin/kexin type 9), an important regulator of lipid metabolism in the liver." (PMID 39531449, 2024). "Treatment with an AAV to upregulate Pcsk9 in the liver is a recently developed atherogenic model that can induce hyperlipidemia and lesion formation in mice fed an AD without the requirement of crossbreeding into an atheroprone background." (PMID 37086367, 2023). "Our data showed that PCSK9 inhibition by alirocumab ameliorated hyperlipidemia, but it did not improve the hepatic inflammation and liver fibrosis." (PMID 35806383, 2022). "Presently, due to their connections to the hepatic environment and hyperlipidemia, respectively, the primary objective of this study was to investigate a potential relationship between TMAO and PCSK9 in order to explore a novel mechanism linking TMAO and CVD risk." (PMID 36557234, 2022). "Similar reductions in post-prandial lipemia were reported for the PCSK9 antibody evolocumab in a non-randomized trial with 15 participants suffering from type-2 diabetes." (PMID 35052871, 2022). "In addition, RYR produced and very poor effects in PCSK9 when compared to BPF, thereby confirming that BPF is able to produce a better protection against diet-induced hyperlipidemia." (PMID 35276836, 2022). "Furthermore, with PCSK9 > 255.05 ng/ml, patients with PNS were more prone to develop hyperlipidemia." (PMID 32349585, 2020).
hyperlipidemia (continued). "Therefore, complete knockout of hepatic PCSK9 is not available, and we only demonstrated that hepatic PCSK9 knockdown attenuates hyperlipidemia-induced liver inflammation." (PMID 39963241, 2025). "Here, we found that conditional knockdown of hepatic PCSK9 suppressed the levels of phosphorylated PI3K, AKT, NF-κB, and AP-1 proteins following hyperlipidemia challenge; this result suggests that PCSK9 knockdown may reduce inflammation by inhibiting the PI3K/AKT signaling pathway." (PMID 39963241, 2025). "Future studies may extrapolate this work by investigating β-cell survival and function changes in response to new therapeutic approaches such as the combined use of proprotein convertase subtilisin/kexin type 9 (PCSK9) inhibitors and statins for treating hyperlipidemia." (PMID 39544235, 2024). "Thus, PCSK9 and IDOL serve as potential therapeutic targets for hyperlipidemia." (PMID 39204178, 2024). "It will also be interesting to examine whether POST1 affects autoprocessing of proprotein convertase subtilisin kexin 9 (PCSK9), which is classified as non-basic proprotein convertases along with S1P and, importantly, serves as an emerging drug target for hyperlipidemia and cardiovascular disease." (PMID 32666500, 2021). "Although the association of some DOCK7, PCSK9 and GALNT2 SNPs and serum lipid levels has been reported in several previous studies, the association of the novel variants and their haplotypes and possible gene–gene interaction with the risk of hyperlipidaemia has never been detected previously." (PMID 26493351, 2016). "If these observations are reproduced in patients on PCSK9 inhibitors treatment is not known, but it could explained the wide impact of these drugs on lipid profile affecting in a moderate way, triglycerides and HDL reinforcing the role of this treatment in patients with combined hyperlipidemias." (PMID 27488210, 2016).